INS (insulin)
Diseases named in the same sentence as INS in open-access papers (continued):
Sharing a sentence is not in itself a finding about the gene and the disease.
Hypoglycemia (continued). "Insulin can be considered in those newly diagnosed and with symptoms (hypoglycemia, weight loss, and ketosis), or those with very elevated Hba1c levels (≥10%) and/or glucose levels > 16.7 mmol/L." (PMID 31781665, 2019). "Although insulin lispro was developed in an effort to minimize the risk of hypoglycemia, the number of people with diabetes is predicted to increase to 592 million by 2035." (PMID 31627434, 2019). "While the insulin concentrations were comparable between the conditions, the risk of hypoglycemia was lowest in the 30 min condition." (PMID 31835538, 2019). "The increased risk of severe hypoglycemia with sulfonylureas and insulin was also consistent with their mechanism of action and previous knowledge." (PMID 31237921, 2019). "In summary, this is the first reported case of hypoglycemia associated with co-secretion of insulin by LA and GCA." (PMID 29166433, 2019). "For this reason, the single-hormone AP system delivers a reduced bolus insulin dose at mealtime, to avoid risk of postprandial hypoglycemia." (PMID 31694629, 2019). "Congenital hyperinsulinism (CHI) is characterised by inappropriate insulin secretion causing profound hypoglycaemia and brain damage if inadequately controlled." (PMID 31525223, 2019). "In contrast to most other insulin studies the HypoDeg trial includes only patients at high risk of hypoglycaemia." (PMID 31337371, 2019). "This pair is especially problematic for diabetic patients since “the salicylate increases the effect of sulfonylurea;” It causes hypoglycemia by enhancing insulin sensitivity, particularly in patients with advanced age and/or renal impairment." (PMID 31341958, 2019). "In fact, rodent models of T1DM (Bio-Breeder rats and NOD mice), in which an impaired glucagon response to insulin-induced hypoglycemia is also observed, showed an early and selective loss of sympathetic innervation in the islets of Langerhans." (PMID 31620088, 2019). "GLP-1R agonist is a novel diabetic medication, which has been proven to be safer than basic insulin with a lower risk of hypoglycemia." (PMID 30953513, 2019). "Literature reviews have shown there is a significant association between insulin and hypoglycaemia attacks." (PMID 31638930, 2019). "Of these 99 patients, 61 (61%) cases of hypoglycemia were caused by insulin administration and 38 (38%) were caused by unrecognized malnutrition." (PMID 31539342, 2019). "It provides an effective basal insulin supply and has a lower propensity to cause hypoglycemia as compared to neutral protamine Hagedorn (NPH) insulin, with similar efficacy in glycemic control." (PMID 31890395, 2019). "Due to the pharmacological administration of exogenous insulin therapy, people with T1D frequently engage in exercise under markedly hyperinsulinemic conditions, thus are exposed to a greater risk of hypoglycaemia." (PMID 31428047, 2019). "The reduced hepatic glucose output due to testosterone supplementation to the HFD fed males caused hypoglycaemia in the treated animals in response to the extrinsic insulin." (PMID 31693697, 2019). "Separate cohorts of the PVH-specific MC4R-deficient mice (Mc4rloxP/loxP + AAV-Cre) were subjected to insulin-induced hypoglycemia or 2-DG-induced glucopenia using the same protocol as described for ArcPomc−/− mice." (PMID 30503832, 2019). "Sulphonylureas are insulin secretagogues that increase the risk of hypoglycaemia during moderate to high-intensity exercise." (PMID 31161377, 2019). "Insulin-treated T2D increases the risk of severe hypoglycemia, which is associated with an increased rate of cardiovascular (CV) events and the possible risk of hospitalization for heart failure (HF)." (PMID 31729990, 2019). "The combination of insulin- and contraction-mediated glucose uptake significantly increase their risk for hypoglycemia during and after exercise." (PMID 30787908, 2019).
Hypoglycemia (continued). "Treatment with insulin increases the risk of severe hypoglycemia, which is associated with an increased risk of all-cause mortality and CV events, including stroke, coronary heart disease, CV disease and all-cause hospitalization (including heart failure)." (PMID 31729990, 2019). "Closed-loop systems titrate insulin based on sensor glucose levels, providing novel means to reduce the risk of hypoglycaemia while improving glycaemic control." (PMID 31164368, 2019). "We studied white matter aglycemic injury and found that hypothermia was neuroprotective, suggesting a novel therapy to treat patients suffering from iatrogenic hypoglycemia associated with insulin therapy." (PMID 30834716, 2019). "The insulinotropic effect of DPP-4 inhibitors explains the phenomenon that this class increasingly is replacing the use of sulfonylureas as insulin releasing agents; especially since the intrinsic hypoglycaemia risk of DPP-4 inhibitors is very low." (PMID 31275246, 2019). "For example, insulin therapy and insulin secretagogues can cause a lethal reduction in blood glucose levels resulting in hypoglycaemia." (PMID 31516543, 2019). "Adjustments in basal insulin in conjunction with intermittent fasting need to take into account the patient’s fasting blood sugar as well as the risk of hypoglycemia, including hypoglycemia unawareness." (PMID 31003482, 2019). "Combined the elevated degree of concentration of circulating of insulin propagates an increased risk of exercise-induced hypoglycaemia, which unsurprisingly prevails as a major barrier to exercise participation." (PMID 31428047, 2019). "Another possible therapy is islet transplantation, a type of cellular replacement therapy that can rescue the production of an appropriate amount of insulin in a glucose-dependent manner and thereby diminish the risk of hypoglycemia." (PMID 30781427, 2019). "The glucose-lowering effect of insulin persists for a long duration and increases the risk of symptomatic hypoglycemia." (PMID 30934740, 2019). "Insulin therapy is usually associated with some side effects, such as hypoglycemia and weight gain, which is aggravated by the lack of patient compliance with adequate treatment, since the condition is more common in children and adolescents." (PMID 31156453, 2019). "The diagnostic criteria rely on inappropriate insulin secretion (0.30 pmol/l), which is consistent with hypoglycemia (2.2 mmol/l) and subsequent tumor localization." (PMID 32009878, 2019). "Type 1 diabetic (T1D) patients are at increased risk of developing life-threatening hypoglycemia due to the imperfect regulation of exogenously administered insulin." (PMID 31013147, 2019). "Deficient gluconeogenesis, along with malnutrition, deficient catecholamine release, and impaired renal insulin degradation and clearance, can contribute to decreasing insulin requirements and frequent hypoglycemia among patients with ESRD." (PMID 31828166, 2019). "Insulin can increase the risk of malignancy in addition to the side effects of weight gain and hypoglycaemia." (PMID 31687406, 2019). "Diabetic patients have an increased risk of developing hypoglycemia particularly when treated with insulin or insulin secretagogues." (PMID 31166971, 2019). "In this study, items that addressed increased risk of hypoglycemia (Item 9) and weight gain (Item 10) after insulin injection were deleted after item analysis." (PMID 30807441, 2019). "The only means for management of ID is insulin therapy; yet, this approach is sub-optimal and causes life-threatening hypoglycemia." (PMID 31391467, 2019). "Of the two groups between glyburide and insulin, glyburide had a higher risk of neonatal hypoglycemia compared with insulin (RR, 1.76; 95% CI, 1.32 to 2.36; P < 0.001), which is the same as the study." (PMID 31781670, 2019).
Hypoglycemia (continued). "In this crossover study, individuals with T2D who were at risk of hypoglycaemia were randomized to double‐blind treatment with degludec or insulin glargine 100 units/mL (glargine U100) ± oral antidiabetic drugs." (PMID 30891886, 2019). "TI is more rapidly absorbed than subcutaneous insulin therapies, has a shorter duration of action and is associated with less hypoglycemia." (PMID 31470605, 2019). "Critical illness associated hypoglycemia generally occurs as a result of high metabolic consumption with relative insulin excess and insufficient nutritional intake that is seen frequently in critically ill patients." (PMID 31263604, 2019). "Insulin autoimmune syndrome (IAS) is a rare cause of hypoglycemia and is characterized by the presence of insulin autoantibodies." (PMID 31883520, 2019). "Glyburide had a higher risk of neonatal hypoglycemia compared with insulin (RR, 1.76; 95% CI, 1.32 to 2.36; P < 0.001)." (PMID 31781670, 2019). "This insulin trial is one of a few to systematically evaluate the risk of hypoglycaemia by simultaneous adjudication of events, reporting in diaries and observation by CGM." (PMID 31337371, 2019). "The babies of mothers who used insulin or had a high weight gain during pregnancy were associated with severe or persistent neonatal hypoglycemia." (PMID 31023291, 2019). "Skeletal muscle insulin sensitivity is enhanced for up to 48 h following exercise increasing muscle glucose uptake and the risk of hypoglycaemia." (PMID 31161377, 2019). "Since the GLP-1 dependent stimulation of insulin secretion is only present under hyperglycaemic conditions, there is a very low intrinsic risk of hypoglycaemia." (PMID 31275246, 2019). "The risk of hypoglycaemia is increased for diabetics, due to either an impaired response of the alpha cells in the pancreas, or as a side effect of insulin therapy and can require an additional supply of exogenous glucagon to be administered." (PMID 31829209, 2019). "This measure is accompanied by a risk of iatrogenic hypoglycemia, though, especially in intensively treated patients who receive insulin or sulfonylureas." (PMID 30696060, 2019). "Insulin injections are also associated with the risk of local infections, hypoglycemia, skin necrosis and nerve damage." (PMID 31756981, 2019). "Alcohol causes delayed hypoglycemia, which is particularly problematic in diabetics who inject insulin or take certain oral antidiabetic medications, especially if application of antidiabetic drugs is not well-controlled." (PMID 31427589, 2019). "In conclusion, after 52 weeks, the addition of sotagliflozin to optimized insulin therapy was associated with a decrease in overall, nocturnal, and severe hypoglycemia across all HbA1c levels." (PMID 31335194, 2019). "Insulin dose adjustment in T1D is preferentially based on blood glucose monitoring in order to avoid hypoglycemia associated with exercise." (PMID 30781593, 2019). "Of the adverse reactions detected, only hypoglycemia related to insulin use presents a greater risk to the patient and the need for immediate intervention." (PMID 31185941, 2019). "Insulin users had the greatest risk of severe hypoglycemia (SH) compared with TZD and DPP4i users, respectively, whereas TZD users were associated with a higher risk of SH than DPP4i users." (PMID 31877127, 2019). "It has been reported that duration of insulin use, and increasing complexity of insulin regimens, are associated with increased risk of hypoglycemia and hypoglycemia unawareness." (PMID 31775749, 2019). "If deviating from a 24-hour injection interval results in substantial alterations in plasma insulin concentrations, risk of hyper- and hypoglycemia is increased." (PMID 30369394, 2019). "It has been suggested that the risk for hypoglycemia increases in patients with T2DM on combination treatment with both insulin and oral glucose-lowering drugs." (PMID 30815039, 2019).
Hypoglycemia (continued). "Like most other insulin trials, however, these trials only included participants at low risk of hypoglycaemia and accordingly the absolute risk reduction of nocturnal hypoglycaemia with insulin degludec is small." (PMID 31337371, 2019). "Irrespective to the chosen approach for insulin administration, a limiting factor in obtaining tight glucose control is the risk of inadvertent hypoglycemia." (PMID 31261760, 2019). "Diazoxide was also later used to treat hypoglycemia caused by high levels of insulin secreted from inoperable extrapancreatic malignancies." (PMID 29166433, 2019). "The use of some glucose-lowering drugs, specifically sulphonylureas and insulin, is largely limited by the risk of hypoglycemia, which is minimized when using GLP-1RA and SGLT2i21." (PMID 31852920, 2019). "Individuals with T1DM have an inherently higher risk of hypoglycemia due to the hypoglycemic effect of unregulated exogenous insulin therapy." (PMID 31866948, 2019). "There is a practical consideration that administering long-acting insulin in previously insulin-naïve patients brings a risk of hypoglycemia if feeding tubes are accidentally pulled or obstructed." (PMID 31261760, 2019). "Insulinoma is a rare neuroendocrine tumor that causes inappropriate release of insulin, resulting in episodes of hypoglycemia." (PMID 31970038, 2019). "If too much insulin were secreted with insufficient glucose around there is a risk of hypoglycaemia, as we found when titrating the vector dose, which can be lethal." (PMID 30514969, 2019). "Insulin use has caused hypoglycaemia (1.2 - 3.3 (2.5 ± 0.7 mmol/l)) in 20/100 (20%) pt, LOS in ICU 62.1 ± 40.3 vs 37.7 ± 21.4 h, p<0.05." (PMID 30890150, 2019). "Glitazones were associated with a decreased risk of stroke, insulin with an increased risk of serious adverse events, insulin and sulfonylureas with an increased risk of severe hypoglycemia." (PMID 31237921, 2019). "Scatchard plot analysis has revealed that this type of insulin autoantibody has high binding capacity and low affinity, thereby causing remarkable hyperinsulinemia and fasting or late postprandial hypoglycemia." (PMID 30621663, 2019). "Further study is needed to understand the role of previous insulin exposure and hypoglycemia associated with BB use and BB type." (PMID 31775749, 2019). "Costello reported hypoglycemia after resection of pheochromocytoma and implicated enhanced insulin release due to the sudden withdrawal of catecholamines and beta-blocker use." (PMID 31275775, 2019). "Hypoglycemia can also occur due to inanition, hepatic disorders, hormone deficiencies, antibodies to insulin or its receptor, performance of gastric bypass, and tumors (i.e., tumor-induced hypoglycemia [TIH])." (PMID 32025979, 2019). "The most common and potentially fatal of these is hypoglycemia, caused by insulin actions on glucose uptake and storage." (PMID 30698225, 2019). "The short-acting insulin analogues (lispro and glulisine) were associated with a 45% lower risk rate of nocturnal hypoglycemia when compared with regular human insulin (risk rate 0.55, 95% CI 0.40–0.76, 1995 patients, I2 = 84%)." (PMID 30622653, 2019). "There are few data describing risk of hypoglycemia among hospitalized BB recipients who are receiving insulin." (PMID 31775749, 2019). "Fluoroquinolones, the commonly used antibacterials, have been associated with dysglycemia (hypoglycemia and/or hyperglycemia) mainly in patients with diabetes taking either oral hypoglycemic agents or insulin." (PMID 31078137, 2019). "Insulin is the major treatment while is associated with hypoglycaemia and adverse placental, fetal and maternal outcomes." (PMID 31591391, 2019). "The combined data of 22 RCTs showed that short-acting insulin analogues are associated with a decrease in total hypoglycemic episodes, nocturnal and severe hypoglycemia, and post-breakfast, post-lunch and post-dinner glucose levels." (PMID 30622653, 2019).
Hypoglycemia (continued). "Occurrences of 25 types of AE were observed and hypoglycemia corresponded to 20.0% of the total; 60.0% of the complaints about hypoglycemia occurred in the association of “linagliptin with insulin and other oral antidiabetics”." (PMID 31178735, 2019). "The prevalence in the current study is 21.9% in at-risk patients (e.g., those on hypoglycemia-causing medications such as insulin and/or sulfonylureas)." (PMID 30473710, 2018). "Insulinoma is a rare neuroendocrine tumor that causes hypoglycemia due to unregulated insulin secretion." (PMID 29977620, 2018). "Insulin analogs have been widely used in China due to their advantages over traditional human insulin, such as a reduced risk of hypoglycemia, injection time flexibility, and convenience." (PMID 29476413, 2018). "In general, prediction in data sets where the prevalence of the target outcome is low (like insulin-associated hypoglycemia) tends to be challenging." (PMID 29527311, 2018). "The current available insulin therapies decrease blood glucose but are associated with the risk of developing hypoglycemia." (PMID 29595915, 2018). "In insulin-treated patients at high hypoglycaemia risk, nausea, falls and unsteadiness should prompt consideration of hypoglycaemia." (PMID 28918198, 2018). "Consider discontinuing or reducing the dose of sulfonylurea when basal insulin is initiated, as hypoglycemia risk is high when both are used together." (PMID 29527102, 2018). "It is unlikely that DPP4 inhibitors cause hypoglycemia when used alone or in combination with metformin, due to the glucose-dependent effects on insulin and glucagon secretion." (PMID 29535389, 2018). "A major clinical benefit of insulin degludec is that it significantly lowers the risk of hypoglycaemia compared with insulin glargine U100 (100 units/ml)." (PMID 28913543, 2018). "Although insulin and certain oral antihyperglycaemics are the most highlighted causes of hypoglycaemia, several other aetiologies and risk factors have been identified in various studies worldwide." (PMID 29884151, 2018). "Unfortunately, therapeutic inertia—failure to reduce or modify insulin therapy in patients with downward trending blood glucose (BG) readings—is a common cause of insulin-associated hypoglycemia." (PMID 29527311, 2018). "Patients >65 and who are insulin-treated are at the highest risk of hypoglycaemia documented in primary care records, as will be well-recognised by primary care practitioners." (PMID 28918198, 2018). "Sulfonylureas are also established therapies to promote insulin production, but they are associated with risk of hypoglycemia." (PMID 29348454, 2018). "Thirdly, we did not demonstrate the underline mechanisms of older men patients who had a higher risk of nocturnal hypoglycemia when treated using insulin intensive therapy." (PMID 29946148, 2018). "Blood glucose was maintained at safe levels (>70 mg/dL), reducing the risk of hypoglycemia, even after exendin-4 and insulin were systemically absorbed by coadministration with L-penetratin." (PMID 30518944, 2018). "Co-formulation insulin offers the advantage of lower risk of hypoglycemia and nocturnal hypoglycemia." (PMID 29527102, 2018). "Insulin glargine is a long-acting insulin analogue with a more prolonged, consistent duration of action and a lower risk of hypoglycaemia compared to NPH (humane isophane) insulin." (PMID 28803366, 2018). "There is a perception that insulin: represents the last line of treatment and is associated with failure; increases the patient’s self-management burden; and imposes hazards such as hypoglycaemia and weight gain." (PMID 29788908, 2018). "The SPIRIT database was chosen because patients transferred from oral treatment to insulin treatment which heightened the risk of hypoglycaemia." (PMID 28803366, 2018). "These can be utilized with patient-friendly regimens and insulin preparations, which achieve good glycemic control with minimal risk of hypoglycemia and unwanted weight gain." (PMID 29460258, 2018).